EZH2 (enhancer of zeste 2 polycomb repressive complex 2 subunit)
Diseases named in the same sentence as EZH2 in open-access papers (continued):
Sharing a sentence is not in itself a finding about the gene and the disease.
tumor (continued). "Applications of EZH2 IHC have also been explored for mesothelial, breast, prostate, biliary, endocervical, and liver neoplasms, and therefore EZH2 may become a multi-purpose addition to a laboratory’s available immunostains." (PMID 37190202, 2023). "EZH2 expression in After Tumor significantly increased compared to Before Tumor." (PMID 38136558, 2023). "In addition to being an oncogenic driver, EZH2-dependent epigenetic reprogramming modulates tumor-immune infiltrate." (PMID 36900330, 2023). "The hypoxia-induced shift of EZH2 from PRC2 into FOXM1 complexes promoted tumor cell invasion." (PMID 37686402, 2023). "Targeting EZH2 has been proposed as a potential strategy to enhance tumor immunogenicity." (PMID 38077327, 2023). "Meanwhile, miR- 101-3p also targeted EZH2, thereby enhancing tumor suppression." (PMID 37626362, 2023). "Given the profound anti-tumor effects of genetic EZH2 knockdown in combination with therapy-induced senescence in PDAC, we next tested whether small molecule EZH2 inhibitors that are in clinical development could achieve similar responses." (PMID 37142692, 2023). "A recent study showed targeting EZH2 had a tumor suppressor function in DMG tumor bearing mice, which could potentially enhance the radiotherapy." (PMID 37157237, 2023). "Therefore, there is a need to better understand the mechanisms that sensitize cancer cells to EZH2 inhibitors, along with their effects on the tumor microenvironment (TME)." (PMID 36900330, 2023). "Additionally, hub genes such as AXL and EZH2 were also found to be responsible for tumor growth and anti-neoplastic drug resistance/sensitivity." (PMID 36715825, 2023). "Therefore, only when FGFR4 and EZH2 signaling were simultaneously suppressed would YAP expression decline dramatically and ultimately synergistically cause massive apoptosis in tumor cells." (PMID 37085881, 2023). "In line with our results, it has been recently demonstrated that histone methyl transferases such as EZH2 are misregulated or mutated in NHL disease leading to an aberrant methylation of H3K27, and silencing of tumor suppressors contributing to disease progression." (PMID 37770512, 2023). "Thus, both genetic EZH2 suppression and EZH2 methyltransferase inhibitor treatment can augment T/P-induced senescence to potentiate cytotoxic NK and T cell immunity and tumor control in transplanted and autochthonous PDAC models." (PMID 37142692, 2023). "At last, whether BMSC‐exo‐miR‐30b‐5p affects tumour growth in nude mice by regulating the EZH2/PI3K/AKT signalling axis was verified in in vivo experiments." (PMID 37698037, 2023). "Accordingly, the subcellular location of EZH2 in tumor cell has also been concerned by researchers." (PMID 37803297, 2023). "The obtained data indicated that BMSC‐derived exosomal miR‐30b‐5p may promote the apoptosis of NSCLC cells and inhibit the tumour growth in nude mice by inhibiting EZH2/PI3K/AKT axis." (PMID 37698037, 2023). "Interestingly, by analysis of GBM specimens, it was shown that the majority of cells with nuclear Ezh2 were found around tumor vessels and on the invasion front, while cytoplasmic Ezh2 was enriched in tumor core cells." (PMID 35205179, 2022). "This review summarizes the progress on the interaction of PARP and EZH2, focusing on the aspects of DNA damage repair and the direct modification that PARP adds to EZH2, and analyzes the possible relationship between PARP and EZH2 in the tumor immune and metabolic microenvironment." (PMID 36263120, 2022). "For example, EZH2 could promote tumor progression by interacting with SNAI1 and being driven to the promoter of E-cadherin, thus suppressing gene expression." (PMID 35597793, 2022). "EZH2 could also restrain the anti-tumor effect of macrophages and NK cells by suppressing the chemotaxis ability of tumors by reducing the expression level of CXCL10, CCL2, and other chemokines." (PMID 36552722, 2022). "DCEM1 downregulates c-Myc, EZH2, and AR as well as inhibits tumor growth in vivo." (PMID 35653190, 2022).
tumor (continued). "EZH2 is a key transcription factor in tumorigenesis and tumor development." (PMID 35154460, 2022). "EZH2 plays a role in the anti-tumor response of macrophages against mesothelioma cells." (PMID 35163049, 2022). "However, we found that EZH2-mediated tumor metastasis markedly abrogated the expression of SMAD3 K53/333R methylation–deficient mutant cells compared with that of WT SMAD3 cells." (PMID 35085106, 2022). "The results indicated that miR-506-3p might act as a tumor suppressor in OvCa metastasis by downregulating EZH2, suggesting that it could be used as a potential therapeutic target for OvCa treatment." (PMID 35154460, 2022). "Dual EZH2 and BET inhibition reduced colony formation, induced cell cycle arrest and caused apoptosis in PDAC cell lines, better than each individual inhibitor alone, and suppressed tumor growth in xenograft mice models." (PMID 36497404, 2022). "In this context, for the first time, we found that GSK343 treatment was able to modulate the innate immune response, increasing CXCL9, CXCL10 and CXCL11 levels in GB, as a result of EZH2 inhibition, enhancing NK cell migration to tumor sites and consequently NK cell-mediated tumor growth inhibition." (PMID 36430394, 2022). "This study demonstrates the tumor-suppressing role of EZH2 in cancer." (PMID 35236381, 2022). "Yet, administration of the same dose of GSK126 caused MYC depletion and tumor growth inhibition in NCI-H82 xenografts, indicating that GSK126 at these doses may disrupt EZH2-MYC interaction and induce MYC degradation in vivo." (PMID 35013218, 2022). "Since EMT is a putative molecular mechanism that drives tumor migration and invasion, we explored whether the EZH2/miR-138-5p axis is involved in EMT by analyzing levels of EMT markers including E-cadherin, N-cadherin, vimentin, and Snail." (PMID 36071871, 2022). "Variants in the CHEK2, BRCA2 and ATM tumor suppressor genes, as well as the ASXL1 and EZH2 Epigenetic Regulators, may support the self-renewal of the proliferating progenitors." (PMID 35896598, 2022). "EZH2 inhibitors increase the infiltration of T cells in the tumor microenvironment." (PMID 36263120, 2022). "EZH2 generally acts as a tumor promoter; however, owing to its methyltransferase activity, it may also act as a tumor suppressor." (PMID 36419933, 2022). "Given that EZH2-92aa expression endowed GSCs with the ability to evade NK cell cytotoxicity, we next investigated whether EZH2-92aa inhibition can enhance NK cell-induced tumour eradication in vivo." (PMID 35970825, 2022). "Comparing EZH2 staining to tumor differentiation by histology found a robust inverse correlation between EZH2 expression and differentiation with EZH2 overexpression in 36% of well-differentiated tumors, 83% of moderately differentiated tumors, and 93% of poorly differentiated tumors." (PMID 36359771, 2022). "Further investigation is necessary to elaborate the effect of combined EZH2/ATM inhibition on DNA damage-derived cytosolic DNA fragments that could trigger an anti-tumor immune response." (PMID 35715861, 2022). "EZH2 functions to promote tumor cell proliferation, invasion, and metastasis." (PMID 36050791, 2022). "Beyond their direct action through epigenetic antagonism, EZH2 inhibitors could also be used as immunomodulators, and the role of EZH2 in the modulation of the tumor immunogenicity has been extensively reviewed elsewhere." (PMID 35327458, 2022). "Reducing the expression of EZH2 in tumor cells could inhibit proliferation, migration, invasion, angiogenesis, and induce apoptosis." (PMID 35874843, 2022). "Furthermore, EZH2-92aa was overexpressed in clinical GBM tumours and predicted worse OS of GBM patients, suggesting the prognostic role of this protein." (PMID 35970825, 2022).
tumor (continued). "The group of EZH2 knockdown combined with PD1 blocker had significant tumor size regression." (PMID 35912007, 2022). "Using an Ezh2 loss-and-gain-of-function approach in the RCAS-Tv/a system, this study shows that EZH2 could function as a potential tumor suppressor." (PMID 35395831, 2022). "It has been reported that the DNA methylation mediated by DNMT1 and EZH2 silences a lot of genes including miR-200b/a/429 expression and promotes tumor progression, which may help explain why EZH2 depletion has different effects from EZH2 inhibitors sometimes." (PMID 36038549, 2022). "The catalytic subunit of PRC2, EZH2, is routinely overexpressed in oncogenesis, promoting uncontrolled cell growth, as many repressed downstream genes of H3K27me3 are tumor suppressors, but the role of PRC2 and its domains are conflicted in aging." (PMID 35104377, 2022). "Therefore, EZH2 becomes a potential hotspot for a tumor-targeted drug, in order to restore the equilibrium between SWI/SNF and PRC2 complexes by inhibition of the EZH2 methyltransferase activity." (PMID 35326637, 2022). "It has been shown that EZH2 exerts an essential role in the regulation of autophagy in tumor cells." (PMID 35402377, 2022). "In vivo, the inhibition of EZH2 reduces tumor growth rates to various extents." (PMID 35955891, 2022). "Besides, EZH2 silencing by siRNA results in the downregulation of tumor-promoting factors including cyclin D1 and multidrug resistance 1 (MDR1) at protein and mRNA levels." (PMID 35236381, 2022). "Inhibition of EZH2 (an oncogenic histone methyltransferase) could increase the myeloid-derived suppressor cells (MDSCs) in the tumor microenvironment, thereby inhibiting the antitumor immunity." (PMID 35764927, 2022). "Besides, EZH2 is highly expressed in a variety of tumors, promote tumor development by regulating cell cycle, and is related to the degree of tumor malignancy." (PMID 36712870, 2022). "We speculate that in the tumor microenvironment, the host somatic cells (like stromal cells) could foster cell proliferation that may circumvent the effect of EZH2 on cell proliferation in vivo." (PMID 35912007, 2022). "EZH2 promotes cell migration, thus promoting tumor progression." (PMID 36497343, 2022). "EZH2 has attracted increasing interest in different tumor entities." (PMID 35740494, 2022). "In most cases, EZH2 functions as a tumor-promoting factor, while owing to its methyltransferase activity, EZH2 may also function as tumor-suppressor." (PMID 35236381, 2022). "In addition, EZH2 is phosphorylated by AMP-activated protein kinase (AMPK) upon energy starvation, which leads to PRC2 disassembly, cause derepression of tumor suppressor genes, and correlates with better survival in cancer patients." (PMID 35800061, 2022). "Nevertheless, in a prostate cancer model, EZH2 inhibition in tumor organoids was able to induce stimulator of interferon genes (STING)-dependent activation of genes involved in antigen presentation, Th1 chemokine signaling and interferon response, including PD-L1 gene expression." (PMID 35158779, 2022). "These assays demonstrated that EZH2 silencing suppressed tumor growth, in line with prior findings." (PMID 35505294, 2022). "For instance, CAFs secreted vascular endothelial growth factor (VEGF) in the surrounding tumor sites to promote the proliferation and angiogenesis of human umbilical vein endothelial cells (HUVECs) via enhancer of zeste homolog-2 (EZH2) /vasohibin 1 (VASH1) pathway." (PMID 35971182, 2022). "It is thus suggested that EZH2 down-regulation by miRNA-340 is involved in anti-tumor activities." (PMID 35236381, 2022). "Loss of Ezh2 clearly enhanced tumor grade and proliferative index, albeit it did not significantly alter the tumor latency when compared to the EZH2 WT group." (PMID 35395831, 2022).
tumor (continued). "In addition, the results of previous studies on the correlation between EZH2 and lymph node metastasis showed that the correlation was stronger for EZH2-expressing tumor cells in lymph nodes than for matched primary tumor cells." (PMID 35208478, 2022). "EZH2 is a downstream biomolecule which could compete with miR-506-3p to increase tumor aggressiveness." (PMID 35345511, 2022). "This epigenetic antagonism has been best characterized in SMARCB1-deficient MRT models where loss of SMARCB1 is associated with constitutive EZH2 activation and downstream oncogenic activity; in MRT preclinical models, EZH2 inhibition induced durable tumor regression and apoptosis." (PMID 35327458, 2022). "High EZH2 expression and high tumour grade were identified as significantly poorer prognostic factors for OS with a higher mortality risk (hazard ratio 6.992, 95% confidence interval 1.317–37.118, p = 0.022 and hazard ratio 24.863, 95% confidence interval 3.227–191.544, p = 0.002, respectively)." (PMID 36292072, 2022). "Moreover, we examined the phenotype of the macrophages and the expression of CCL2 in EZH2 inhibitor-treated 4T1 tumor tissues by IHC." (PMID 36038549, 2022). "The variability of the EZH2 incidence could be related to the inclusion of tumours with variable grades, different EZH2 cut-off, or detection methods." (PMID 36292072, 2022). "The overexpression of the enhancers of zeste homolog-2 (EZH2) favors tumor progression." (PMID 36077660, 2022). "Another important highlight of EZH2 in cancers that needs to be emphasized is its decisive role in immune cells such as T cells, NK cells, dendritic cells, and macrophages which shape the tumor microenvironment." (PMID 36230683, 2022). "Both PARP and EZH2 have a wide range of biological functions in addition to acting on tumor cells, such as being involved in various cells, including immune cells and adipocytes, and they also have a regulatory effect on tumor metabolism and immune function." (PMID 36263120, 2022). "In a previous study, we found that lncRNA regulates EZH2 expression and epigenetically regulates methylation in the CpG island present in the promoter region of tumor suppressor genes, and this hypothesis was introduced in this study." (PMID 35625973, 2022). "Studies of DMG mouse models have indicated that EZH2 plays a tumor-suppressing role." (PMID 36142368, 2022). "In this regard, previous studies exploring the mechanisms of EZH2-mediated oncogenesis have largely focused on the cell-intrinsic mechanisms by which EZH2 regulates the expression of genes that are necessary for cancer cell proliferation and survival, promoting tumor development and progression." (PMID 36430394, 2022). "Moreover, injection of the EZH2 inhibitor tazemetostat into GSCs treated with propofol markedly reduced tumor size." (PMID 35927718, 2022). "We believe this study expands our understanding of TGFB1/EZH2-mediated tumor metastasis." (PMID 35085106, 2022). "Doxycycline administered in drinking water significantly inhibited tumor growth in EZH2-sgRNA." (PMID 36185457, 2022). "Therefore, EZH1/EZH2 have been used to design drugs for hampering tumor growth and restoring tumor suppressor transcription." (PMID 35846880, 2022). "The FDA-approved EZH2 inhibitor tazemetostat interferes with this mechanism and stops tumor growth." (PMID 35159116, 2022). "Additional studies manifested that EZH2 could serve as an RNA-binding protein (RBP) in tumor progression." (PMID 36494339, 2022). "EZH2 as a major driving force in cancer cell immunoediting mediates immune escape by down-regulating immune recognition and activation, up-regulating immune checkpoints, thus generating an immunosuppressive tumor microenvironment." (PMID 36195655, 2022).
tumor (continued). "However, the impact of EZH2 on the tumor immune microenvironments and the efficacy of immunotherapy is not fully understood in NSCLC patients." (PMID 35912007, 2022). "EZH2-mediated tumor metastasis depends on SMAD3 methylation." (PMID 35085106, 2022). "We also have reported that EZH2 can promote tumor cell growth, metastasis and stemness in GC." (PMID 36401232, 2022). "One possible explanation for the discrepancy between these studies is that EZH2 expression may be a better predictor of tumor grade than mortality, so variations in EZH2 expression across tumors of the same grade are non-predictive of outcome." (PMID 36359771, 2022). "Additionally, we investigated EZH2 protein expression levels in tumor and normal clinical samples by using the HPA database." (PMID 36358967, 2022). "In tumoral mouse models, tumor-infiltrating CD8+ T-cells expressed EZH2, and due to the upregulation of BCL-2, exhibited an anti-apoptotic feature associated with increased survival, which is abolished in EZH2-deficient CD8+ T-cells." (PMID 36135315, 2022). "In addition, we noticed that recent studies indicate that inhibiting EZH2 enhances antigen presentation, immune cell activation, and tumor sensitivity to PD-1 blockade." (PMID 36358967, 2022). "To investigate the effect of EZH2 inhibition in a DMG in vivo tumor model, we established mutant H3.3K27M tumors in the ABC KO mice, and treated intraperitoneal (i.p) with Tazemetostat (EPZ-6438, SelleckChem, 400 mg/kg b.w.)for 7 days to enable drug penetration through the blood–brain barrier." (PMID 35395831, 2022). "The interaction between ncRNAs and EZH2 signaling in TME determines tumor progression." (PMID 35236381, 2022). "Moreover, OGT is associated with TETs to control O-GlcNAcylation of histone H2B for activation of gene transcription, while OGT is coordinated with EZH2 to modulate H3K27me3 for silence of tumor suppressor genes." (PMID 35935878, 2022). "However, antithetical EZH2 functions do not only occur among different tumor entities but are also evident within one tissue type." (PMID 35884510, 2022). "And tons of literature have reported the important role of TAMs, whose polarization state and accumulation significantly correlate with tumor progression, so we tried to explore the relationship between EZH2 expression and TAMs polarization in clinical BC patients at first." (PMID 36038549, 2022). "Thus, we further characterized the relationship between EZH2 expression and the infiltration levels of tumor-infiltrating immune cells in HCC tissues." (PMID 35627262, 2022). "However, there are evidence showing that lncRNAs can also inhibit EZH2 signaling to function as tumor-suppressor factors." (PMID 35236381, 2022). "Therefore, SMYD2 stimulated tumor growth and depressed cell senescence and apoptosis by regulating the EZH2/TET1 axis." (PMID 35668081, 2022). "We conducted genomic analysis using paired tumor tissue samples at diagnosis and relapse and observed frequent occurrence of mutations in CREBBP and EZH2, which are involved in lymphomagenesis and progression as a chromatin regulator, as well as mutations in BNFRSF14 and BCL2 as previously reported." (PMID 36199784, 2022). "However, the combination of EZH2 inhibitors with PARP inhibitors can also negatively affect immune cells in the tumor microenvironment, such as macrophages." (PMID 36263120, 2022). "Despite that EZH2 could promote HCC development by repressing the transcription of some anti-tumor miRNAs and genes, the global regulatory mechanisms of EZH2 in HCC were poorly understood." (PMID 36578923, 2022). "Clinical trial studies are now emerging based on the therapeutic inhibition of the histone methyltransferase EZH2, a key epigenetic regulator found to suppress the immunogenicity of tumour cells via transcriptional repression of genes involved in IFNγ response and antigen presentation." (PMID 35327375, 2022). "Recently, PTMs of EZH2 have also been shown to exert tumor-suppressive effects." (PMID 36076977, 2022).